ENSG00000280371 ( gene)
Diseases named in the same sentence as ENSG00000280371 in open-access papers (continued):
Sharing a sentence is not in itself a finding about the gene and the disease.
tumor (continued). "Indeed, it has been shown that miR-96 (7q32.2) can function either as oncogene or tumor suppressor gene in different tumor types." (PMID 25071021, 2014). "Ectopic expression of HSPB7 significantly impaired colony-forming ability for 5 RCC cell lines, indicating that HSPB7 may function as a tumor suppressor gene." (PMID 24585183, 2014). "Although the activation of Stat5 has been associated with tumourigenesis of several solid tumours, in the liver, Stat5 has a role as tumour promoter but it seem to have also a potential role as tumour suppressor gene; therefore, the role of Stat5 in hepatocarcinogenesis is still debated." (PMID 25225571, 2014). "These opposing findings substantiate the hypothesis that miR-141 may play different roles as an oncogene or a tumor suppressor gene in different cancer types." (PMID 24551096, 2014). "SLIT2 has been postulated for several years to act as a tumour suppressor gene in several cancers." (PMID 23671423, 2013). "Finally, the klotho gene encoding the obligate co-receptor for FGF-23 is also a putative tumour suppressor gene, further implying the link between Pi regulation and carcinogenesis." (PMID 23706176, 2013). "Furthermore, autophagy is a novel evolutionarily conserved function of the PKR pathway that is targeted by viral virulence gene products and in cancer where anti-tumor effects induce autophagosome formation through PKR activation." (PMID 24330807, 2013). "The location of human SF-1 in the region of 9q33 supports our hypothesis that SF-1 is a candidate tumor suppressor gene in the ovary and that abolished or aberrant SF-1 expression in OSE cells may promote tumor growth." (PMID 23291911, 2013). "RARRES1 is a retinoic acid receptor that acts as a vital tumor suppressor gene." (PMID 23922792, 2013). "According to previous studies, CDKN2B may act as a tumor suppressor gene and a potential effector of TGFβ-induced cell-cycle arrest." (PMID 24098334, 2013). "In such tumours, E-cadherin acts as a typical tumour suppressor gene." (PMID 22973534, 2012). "The NIH3T3 transformation data also suggest that Mybbp1a might be able to act as a tumor suppressor gene in some contexts." (PMID 23056166, 2012). "One of the reported targets of miR-205 is a critical tumor suppressor gene, PTEN." (PMID 22514717, 2012). "Notably, the roles of miR-100 in different cancers are quite contradictory as it can behave either as an oncogene or a tumor suppressor gene, depending on the tumor type examined." (PMID 23173870, 2012). "Additionally, Fhit suppresses tumourigenicity in cancer cell lines which implies conclusively that FHIT is a bona fide tumour suppressor gene." (PMID 22295218, 2011). "Genetic analysis of tumor samples indicates that FH acts as a tumor suppressor gene." (PMID 22087286, 2011). "Interestingly, the overlap of all three tumor groups included the region containing INTS6, an annotated tumor related gene (also known as DICE1, Protein deleted in cancer 1)." (PMID 20735817, 2010). "THBS4 may act as a tumour suppressor gene, demonstrated by its suppression of tumour colony formation in vitro." (PMID 20846368, 2010). "In addition, we identified relevant cancer-related target genes and pathways targeted by miR-218, supporting a potential role as a tumour suppressor gene for NSCLC, especially SCCs." (PMID 20838434, 2010). "These suggest that IGF-I may promote tumor cell growth, while IGFBP-3 acts as a tumor suppressor gene." (PMID 19549343, 2009). "Here I discuss some facts and thoughts that support the idea that p73 could still be a tumor suppressor gene." (PMID 17407586, 2007). "The facts that TA-p73 can induce apoptosis and it is hypermethylated in tumors of lymphoid origin indicate that this could function like a tumor suppressor gene." (PMID 17407586, 2007).
tumor (continued). "Since the hyd gene, which encodes the proposed Drosophila ortholog of EDD, was originally identified as a tumor suppressor gene, these findings indicate that deregulation of EDD activity could contribute to tumor development." (PMID 18047743, 2007). "If a particular miRNA targets key tumor suppressor genes, it is supposed to be an oncogene; but, if a miRNA targets an oncogene, it might be viewed as a tumor suppressor gene." (PMID 18079974, 2007). "PRKAR1A is a key component of the cAMP signaling pathway that has been implicated in endocrine tumorigenesis and could, at least partly, function as a tumor suppressor gene." (PMID 16756677, 2006). "However, one note of caution must be added in that STIM1 was initially identified as a candidate tumour suppressor gene and the consequences therefore of long term inhibition of STIM1 expression need to be explored further." (PMID 16987424, 2006). "A novel finding here was the increased expression at 1 dpi of CCAAT/enhancer binding protein (C/EBP)-δ belonging to C/EBP (bZIP) family, which couples extracellular signal transduction pathways to numerous cellular processes and is a potential tumour suppressor gene." (PMID 16318630, 2005). "The amplification of this gene seems contrary to its putative role as a tumor suppressor gene." (PMID 16004614, 2005). "Thus, it is conceivable that ADAR2 may serve as a tumor suppressor gene, regulating glycolipid metabolism and proliferation in GBM cells." (PMID 39794701, 2025). "Therefore, DDX3 may function as an oncogene or a tumor suppressor gene by regulating the expression of cancer‐related miRNAs in human cells." (PMID 39543456, 2025). "DDX3 may act as either an oncogene or a tumor suppressor gene in different types of cancer." (PMID 39543456, 2025). "Here, we evaluated the tumor morphology and immunohistochemical expression of CDH17 and CLDN18 in 25 CD-SBNs and potential relationships with gastric differentiation as indicated by MUC5AC and MUC6 immunohistochemistry, wnt pathway mutations, and mismatch repair gene protein immunohistochemistry." (PMID 39164422, 2025). "It indicated that TSHZ3 may act as a tumor suppressor gene in LUAD." (PMID 40264773, 2025). "Additionally, the molecular mechanism by which LSAMP functions as a tumor suppressor gene by modulating known oncogenic pathways may provide new opportunities for treating patients with LSAMP associated malignancies." (PMID 39595156, 2024). "Therefore, we hypothesized that FN1 in tumor cells may be a key macrophage-regulated ECM gene that promoted enzalutamide resistance in bone-metastatic PC." (PMID 36749798, 2023). "This is probably because OAS1 may act as a tumor suppressor gene in other biological processes, such as cell proliferation, metastasis and drug resistance in BLCA, although OAS1 protects an immunosuppressive TME in BLCA, and these guesses need to be verified in the future." (PMID 37746262, 2023). "In summary, ZDHHC11B may act as a tumor suppressor gene in LUAD." (PMID 37434393, 2023). "In conclusion, our findings uncovered that CASC2 could act as a tumor suppressor gene and inhibit cell proliferation, migration, and invasion through binding to miR-155, thus increasing the expression of its target gene SOCS1, demonstrating the ceRNA function of CASC2." (PMID 36816357, 2023). "Therefore, unlike DKK 1, 2, and 4, there is still some debate about whether DKK3 is an oncogene or a tumor suppressor gene." (PMID 37149563, 2023). "Hence, our data suggest that KLF2 may serve as a tumor suppressor gene in the majority of common tumors." (PMID 37123417, 2023). "Evidence is accumulating that PRUNE2 might act as a tumor suppressor gene." (PMID 36645410, 2023). "Therefore, we assumed that the target gene of L3MBTL2 might be a tumor suppressor gene with a certain role in cancer." (PMID 35521536, 2022). "However, KRT17 is underexpressed in some tumors, and it is considered that KRT17 may play a role as a tumor suppressor gene in these tumors." (PMID 35281081, 2022).
tumor (continued). "YTHDF1 could act as an oncogene or a tumor suppressor gene in tumors." (PMID 35197112, 2022). "Previous studies indicated that GATA4 might act as a putative tumor suppressor gene." (PMID 36588538, 2022). "As a tumor-related gene, TXNDC12 may be used as a new prognostic judgment molecule." (PMID 34629960, 2021). "Therefore, combining the results from cell viability data in vitro, CYP39A1 might serve as a tumor suppressor gene in HCC." (PMID 35003516, 2021). "The results show that ANKRD11 may be a tumor suppressor gene." (PMID 34604130, 2021). "Considering the extensive expression of Porf-2 in the brain and many peripheral tissues, including testes, liver, kidney, prostate, and placenta, and its downregulation in several human tumors, Porf-2 may function as a potential tumor suppressor gene in several systems." (PMID 32676454, 2020). "Therefore, large-scale studies are required to fully dissect the functions of PDK4 in tumor progression and the underlying mechanisms in a variety of human tumor types, which will explain why PDK4 acts as an oncogene or a tumor suppressor gene in various cancers." (PMID 32489458, 2020). "Additionally, a high expression of WT1 (Wilms tumor gene) mRNA in the aqueous humor was discovered." (PMID 31977890, 2020). "Although GEMMs are suitable for investigation of whether a certain gene alteration induces tumor formation or whether an altered gene functions as an oncogene or a tumor suppressor gene, the generation and maintenance of such models are time-consuming and require a considerable amount of effort." (PMID 33348616, 2020). "Therefore, it is tempting to speculate that in CRC, MSX1 represents a tumor-promoting gene with some essential function." (PMID 30733598, 2019). "However, SPP2 is generally lowly expressed in tumors, suggesting that SPP2 may serve as tumor suppressor gene." (PMID 31849319, 2019). "Moreover, BMP-2 is considered a putative tumour-suppressor gene in several cancer types." (PMID 30013089, 2018). "The functional studies indicated that HADHB might act as a tumor suppressor gene." (PMID 29507648, 2018). "Interestingly, Notch-1 may act as an oncogene or a tumor suppressor gene even within the same tumor type, and recently, it has been implicated in induction of cellular senescence mediated by p16 and p21." (PMID 29618945, 2018). "In addition to regulation of myeloid cell activation and various inflammatory diseases, role of KLF2 is also emerging as a potential tumor suppressor gene owing to its roles in the inhibition of proliferation, migration and angiogenesis and in the induction of apoptosis, senescence and adhesion." (PMID 29125549, 2017). "Furthermore, overexpression of AP-2α has been shown to suppress tumorigenicity suggesting that AP-2 α may function as a tumor suppressor gene." (PMID 29100274, 2017). "Taken together, HOTAIRM1 maybe function as a tumour suppressor gene in CRC." (PMID 27307307, 2016). "Finally, our results suggest that Wnt7A is possibly a novel tumor-suppressor gene in MPM." (PMID 25632963, 2015). "Furthermore, the Y chromosome gene TMSB4Y may be a tumor suppressor gene that normally functions through its direct interaction with β-actin, which in turn regulates cell morphology and cell proliferation." (PMID 26702755, 2015). "However, a study reported that HOTAIR induces repressive chromatin status by promoting the formation of H3K27, suggesting that HOTAIR may function as a tumor suppressor gene by inhibiting proliferation of cancer stem cells." (PMID 25303230, 2014). "Thus, hBD-2 is likely to be a putative tumor-suppressor gene." (PMID 24927104, 2014). "On the other hand, TRIB2 may serve as a tumor suppressor gene." (PMID 24191888, 2013).
tumor (continued). "Our study provides evidence that GPER-1 may be a tumor suppressor gene." (PMID 23849542, 2013). "What’s more, there are evidences to believe that GSTP1 methylation could trigger “epigenetic catastrophe” which involves hypermethylation of associated genes including APC (a tumor suppression gene), and RAR-beta (tumor suppressor gene involved in cell cycle and apoptosis)." (PMID 24086370, 2013). "Our results suggested that the LEPREL1 might be a tumor suppressor gene." (PMID 24319452, 2013). "As a tumor suppressor gene, miR-122 is downregulated in HCC cell lines and tumor tissues, leading to the activation of the Wnt/β-catenin pathway, thereby promoting the formation and progression of HCC." (PMID 39935848, 2024). "Only in one primary tumor, we detected cn-LOH at the chromosomal region 3p21.31-p21.1, which harbors the tumor suppressor gene von Hippel-Lindau (VHL)." (PMID 38010391, 2023). "However, BCL2 may function as an oncogene or as a tumor suppressor gene in various types of cancer." (PMID 38003498, 2023). "Thus, we speculated that SIRT5 may be an important tumor suppressor gene." (PMID 37096064, 2023). "Treatment with the methylation inhibitor 5‐aza‐dC promotes GSDME expression and inhibits tumor cell proliferation and tumorigenesis, suggesting GSDME as a novel tumor suppressor gene in CRC." (PMID 37125240, 2023). "For example, DEFB1, the human antimicrobial peptide defensin β 1, is considered as a potential tumor suppressor gene and has been shown to mediate PI3K/mTOR signaling, thereby leading to death of tumor cells." (PMID 35938006, 2022). "In accordance with the result that IGF-2 promotes the growth and proliferation of tumor cells, IGF-2R is considered to be a tumor suppressor gene during cancer occurrence and development." (PMID 36358907, 2022). "Thus, we hypothesized that FBXW7 may act as a tumor-suppressive gene in CC." (PMID 35094292, 2022). "However, it is still unknown whether P63 is a tumor suppressor gene or an oncogene." (PMID 33936229, 2021). "In contrast, when transplanted subcutaneously in mice, three HOMCs with NF2 knockdown formed a tumor mass, confirming that NF2 is an important tumor suppressor gene in MM cells." (PMID 34663305, 2021). "An epigenetic study of HCC also confirmed ESR1 as a tumor suppressor gene, with up to 83% of HCC patient tumors demonstrating ESR1 promoter hypermethylation and predicting tumor progression." (PMID 34881186, 2021). "While many miRNAs have been demonstrated to inhibit tumor formation and/or growth, the tumor suppressor miRNAs mentioned in both the literature and in this review may not be a “classic” tumor suppressor gene that has been demonstrated to cause tumor formation after biallelic inactivation." (PMID 33562727, 2021). "Pertaining to metastasis, research shows that suppression of the tumor suppressor gene, epithelial cadherin (CDH1), is a key factor in EMT as it allows for the tumor cell to detach from its primary tumor site and metastasize in a secondary site." (PMID 32316322, 2020). "The tumor growth assay showed that LINC01088 significantly inhibited tumor growth, implying that LINC01088 was a tumor suppressor gene, although its mechanism remained unclear." (PMID 29440672, 2018). "Thus, whether UPP acts as an oncogene or tumor suppressor gene mainly depends on the context." (PMID 27121050, 2016). "Moreover, many studies have indicated CSMD1 could be a tumor suppressor gene." (PMID 26076954, 2015). "As a tumor suppressor gene, PTCH1 inhibits tumor cell growth and motility by blocking the Hh signaling pathway." (PMID 24961235, 2014). "To explore TAGLN and HDAC2 expression in GBM patient surgical specimens, we performed IHC staining and observed that HDAC2 (which is a hypoxia‐related gene), TAGLN, CA9 (a hypoxic marker), and HIF1α were all located in GBM tumor cell nuclei and highly expressed in pseudopalisades (upper)." (PMID 38087889, 2024).
tumor (continued). "First, we found that the expression level of KLF7 is higher in PCa tissues of patients, and the expression of KLF7 is positively correlated with tumour-promoting gene IL-6, while it is negative correlated with another tumour-suppressor gene p21." (PMID 37170248, 2023). "Many recent studies have shown that SASH1 is ubiquitously expressed in most normal tissues but is decreased or absent in tumor tissues, supporting its function as a tumor inhibitory gene." (PMID 36286186, 2023). "Downregulation of nCLU expression was found to enhance tumor formation, therefore leading to the conclusion that CLU might also be a tumor and metastasis suppressor gene." (PMID 37685987, 2023). "Although FEZ2 is dysregulated in some types of cancers, there is no research mentioned that FEZ2 functions as an oncogene or tumor suppressor gene in PDAC." (PMID 35036176, 2022). "SFRP2 is a secreted key inhibitor of non-canonical Wnt signaling and is considered a tumor suppressor gene depending on the organ/cellular context." (PMID 35892888, 2022). "The presence of the RheoSwitch construct in the B16-RS cells enabled us to amplify and detect the RheoActivator element, which served as a tumor cell-specific marker, and was normalized to the expression of the 60S acidic ribosomal protein P0 (RPLP0), used as a house-keeping gene." (PMID 34830742, 2021). "With regard to HCG11, it has been identified to be aberrantly expressed in some cancers and function as an oncogene or a tumor suppressor gene, not including OS yet." (PMID 34518440, 2021). "Our studies in different RCC cell lines indicated that the absence of the tumour suppressor gene pVHL induced a decrease in the expression of the tumour and angiogenesis inhibitor TSP-1." (PMID 31980715, 2020). "AMPK suppresses tumor survival through inhibition of mTOR by increasing the expression of p-TSC2, a tumor suppressor gene, and leads to the inactivation of AKT and lipopolysaccharide (LPS)-induced IL-6/JAK2/STAT3 signaling in triple-negative breast cancer (TNBC)." (PMID 31952344, 2020). "In respect to this, ELF2B acts in a dominant negative fashion compared to ELF2A and as a putative tumour suppressor gene." (PMID 28351373, 2017). "Furthermore, it has been reported that LIFR is a tumor suppressor gene in HCC and its down-regulation in tumor tissues is mostly dependent on promoter hypermethylation." (PMID 25749520, 2015). "In this picture, CD146 appears as a prometastatic factor associated with poor-prognosis histoclinical features, rather than as a tumor suppressor gene." (PMID 19123925, 2009). "In addition, Lu/BCAM may act as a tumor suppressor gene, as demonstrated in thyroid cancer where Lu/BCAM is downregulated and negatively correlated with tumor growth." (PMID 40332051, 2025). "In addition to that, ECM‐related gene such as MMP9 and MUC5B were prominently upregulated in poorly group, indicating that the expression of these genes in macrophages plays a pivotal role in influencing tumour differentiation." (PMID 40847563, 2025). "Classical protein tyrosine phosphatase nonreceptor type 12 (PTPN12) has been extensively studied to decipher its mechanism as a tumor suppressor gene in various human carcinomas; however, there is no comprehensive elucidation of the PTPN12 expression and its regulatory mechanisms in LSCC." (PMID 37333450, 2023). "Similarly, miR-20b, a member of the miR-106b-25 cluster cannot be classified as either an oncogene or tumor suppressor gene." (PMID 36994208, 2023). "Our results suggest that in LGG, unlike in GBM, DKK3 may also act as a tumor suppressor gene to some extent in relation to Wnt/β-catenin signaling." (PMID 37149563, 2023). "However, PAG1 can be considered an oncogene or a tumor suppressor gene, depending on tumor type, and its expression is not homogeneous across the different types of cancers." (PMID 34141616, 2021).